FPR2 (formyl peptide receptor 2)
Diseases named in the same sentence as FPR2 in open-access papers (continued):
Sharing a sentence is not in itself a finding about the gene and the disease.
tumor (57 papers, 2013 to 2026). "Instead, it reshapes the immunosuppressive tumour microenvironment by activating FPR2+ tumour-associated macrophages (TAMs)." (PMID 42145073, 2026). "This calls for further studies to elucidate the mechanisms underlying the capacity of Fpr2 to promote M1 polarization of macrophages that limit tumor growth." (PMID 32038501, 2020). "Another classical chemoattractant GPCR, the FPR1 variant FPR2, has also been reported to participate in recruiting MSCs into tumor tissues to promote the formation of neovasculature in response to tumor-derived ligand LL-37." (PMID 25110692, 2014). "Furthermore, increased FPR2 expression is associated with rapid tumor progression and a worse prognosis for patients with colon and epithelial ovarian cancer." (PMID 40733247, 2025). "There are several receptors that may be associated with tumor-promoting functions of hCAP18/LL-37, such as FPR2, EGFR, and IGFR1 receptor." (PMID 35039485, 2022). "Along these lines, AnxA1-deficient mice displayed reduced breast cancer growth and enhanced survival, and it was proposed that AnxA1 binding to FPR2 on macrophages, influencing their polarization and infiltration of solid tumours, would be the underlying cause for enhanced tumour progression." (PMID 33810523, 2021). "Indeed, analysis of tumor infiltrating macrophages from in situ tumor tissue following LL-37 treatment showed macrophages characterized by high IL-10 and low IL-12p35 expression levels, thereby implicating FPR2 signaling in regulating the phenotype of tumor-associated macrophages." (PMID 36817589, 2023). "Tumour-derived SAA1 reprograms TAM through FPR2-mediated JAK2-STAT3 signalling to induce an immunosuppressive phenotype." (PMID 42145073, 2026). "FPR2 is also highly expressed in colorectal cancer, promoting the prevention of tumor apoptosis and the progression of the invasive process." (PMID 40733247, 2025). "FPR2 agonists, including Resolvin D1 and Lipoxin A4, have demonstrated the ability to promote repolarization of M2 to M1 macrophages and enhance anti-tumor immunity." (PMID 41150752, 2025). "Particularly attractive are the immunomodulatory role of FPR2 by regulating proinflammatory and anti-inflammatory activities and the association of FPR3 with tumor immunity, indicating its availability as a prognostic biomarker in cancer." (PMID 40103822, 2025). "For example, neutrophils and NK cells showed significant interactions with tumour cells through pathways such as MIF‐(CD74 + CXCR4) and ANNEXIN‐(FPR1 + FPR2), which are known to modulate immune responses and tumour progression." (PMID 40099956, 2025). "To validate the transcriptional data, we performed immunofluorescence microscopy on multiple advanced-stage MF samples staining for FPR2 and FCN1 to identify MF-specific tumor-associated macrophages (TAMs) and CLEC4C and LILRA4 to identify pDCs." (PMID 37669110, 2023). "In summary, some key genes were identified by a variety of bioinformatics methods in this study and the roles of a few genes have been deeply studied in tumor biology, such as FPR2 and TLR4." (PMID 35675043, 2022). "In contrast, LL-37 promotes tumor progression in some contexts, depending on its binding to FPR2 and P2X7R in pancreatic cancer or IGF-1R in breast cancer." (PMID 34867962, 2021). "Studies have shown that FPR2 plays a critical role in antitumour host immunity by limiting macrophage recruitment into tumours and sustaining macrophages in an M1 phenotype." (PMID 34930387, 2021). "FPR2 stimulation promotes tumor cell invasion by evoking MEK/ERK pathway, which represents a common event in cancer progression." (PMID 32471307, 2020). "First, as found by qPCR, Fpr2 was up-modulated in XO ki activated macrophages whereas arg was down-modulated, recapitulating the regulation previously found in tumor infiltrating macrophages." (PMID 31659168, 2019).
tumor (continued). "The findings of the two experimental studies described in the section on tumor growth and metastasis, suggest that FPR2-ERK signaling, TGF-β, and NR4A1 are candidate targets for novel treatments of overt metastatic disease." (PMID 30213113, 2018). "When the implantation was performed at 1 × 104 cells/mouse, not only the smaller and lighter xenograft tumors but also the reduced tumor-forming ratio (4/5 vs 5/5) were observed in FPR2-knockdown GC cells as compared to mock cells." (PMID 28600569, 2017). "In our experiments, we also found that FPR2 deletion markedly decreased the tumor formation in nude mice." (PMID 28600569, 2017). "In a separate set of samples, quantitative analysis of FPR2 mRNA in 6 fresh surgical specimens indicated that 5 out of 6 tumor tissues had high level of FPR2 expression as compared with their adjacent normal tissues." (PMID 28600569, 2017). "The mast cells and neutrophils in the peritumoral and tumor sections revealed high expression of ANXA1/FPR2." (PMID 25490767, 2014). "The activation of the PI3K-Akt/PKB pathway mediated by FPR2 supports tumor cell survival and proliferation in several cell types." (PMID 23549262, 2013). "Conversely, FPR2 antagonists may be beneficial in contexts where excessive inflammatory responses drive tumor progression." (PMID 41150752, 2025). "These included the chemokine signaling pathway, cytokine-cytokine receptor interaction, JAK-STAT signaling pathway, and NOD-like receptor signaling pathway, indicating FPR2’s significant role in immune modulation and inflammation within the tumor microenvironment." (PMID 41376620, 2025). "Additionally, FPR2 influences the tumor microenvironment by stimulating the secretion of Th2 cytokines, such as IL-4 and IL-10, which drive the polarization of macrophages into the M2 phenotype." (PMID 40330466, 2025). "Several studies have shown that FPR2 stimulates tumor cell invasion and proliferation." (PMID 36471379, 2022). "Alternatively, increased binding of AnxA1 released from cancer cells to FPR2 on regulatory T cells may impede anti-tumour immune responses." (PMID 33810523, 2021). "Furthermore, we suggest that FPR2-induced MEK2 phosphorylation promotes tumor cell invasion by evoking MEK/ERK pathway." (PMID 32471307, 2020). "Fpr2 promotes the M1 polarization of TAMs and limit tumor growth a mouse LLC models." (PMID 32038501, 2020). "Pathology studies of tumor tissues detected increased number of TAMs in tumors grown in Fpr2 KO mice and the macrophages isolated from Fpr2 KO mice showed a more-potent chemotactic response to LLC-derived supernatant that contained high concentrations of the chemokine CCL2." (PMID 32038501, 2020). "Interestingly, we found FPR2 expression is significantly related with the location of the tumor (p = 0.002)." (PMID 28724995, 2017). "The FPR2 expression level was related with the location of the tumor (p < 0.05)." (PMID 28724995, 2017). "Co-localization of ANXA1/FPR2 was detected in the mast cells, neutrophils, and tumor cells." (PMID 25490767, 2014). "We showed that ANXA1 protein may control tumor growth in a paracrine manner that is mediated by the receptor FPR2/ALX." (PMID 25490767, 2014). "MSCs may be recruited into the tumor through FPR2, CCR2, CXCR1, CXCR2, CXCR4, CXCR6, and CX3CR1 depending on the types and locations." (PMID 25110692, 2014). "Integration of the in vivo and in vitro data showed that ANXA1 may be effective in the regulation of tumor growth and metastasis through paracrine mechanisms mediated by FPR2/ALX." (PMID 25490767, 2014). "ANXA1 may contribute to the regulation of tumor growth and metastasis through paracrine mechanisms that are mediated by FPR2/ALX." (PMID 25490767, 2014). "In contrast to wild-type (WT), Fpr1-/-, and Fpr2-/- mice, neutrophils were almost completely absent in 4T1 tumors from Cxcr2-/- mice, indicating a dominant role for CXCR2 in the recruitment of tumor-associated neutrophils, leading us to use Cxcr2-/- mice for further studies." (PMID 41977328, 2026).
tumor (continued). "GSEA further revealed that FPR2 is primarily involved in inflammatory and chemokine signaling, while PDGFRB is associated with pathways regulating cell adhesion, migration, and epithelial-mesenchymal transition, underscoring their roles in immune modulation and tumor metastasis." (PMID 41376620, 2025). "FPR2 also contributes to fibroblast homeostasis through ANXA1-mediated signaling within the tumor microenvironment (TME), and disruption of this axis facilitates the transformation of fibroblasts into cancer-associated fibroblasts (CAFs), contributing to tumor progression." (PMID 41376620, 2025). "Furthermore, the observation that PKN2 can phosphorylate, and thereby regulate, several cytoskeletal substrates enhancing actin polymerization and contributing to tumor cell migration, strongly suggests that FPR2 signaling plays a key role in these molecular mechanisms." (PMID 32471307, 2020). "Indeed, it has been reported that ANXA1 associated with NF-κB FPR2 activation by distinct ligands can trigger the GPCR-mediated signalling cascade to modulate cytokine signalling and tumour microenvironment, resulting in macrophage polarization and tumorigenesis." (PMID 29263330, 2017). "These pathways were taken over in the tumor environment by ECM pathways and the immune ANXA1‐FPR1 and FPR2." (PMID 40674254, 2025). "Ac2-26 has been shown to regulate leukocytes and other tumor cell migratory events through interactions with formyl peptide receptors (FPRs), and thus we examined the expression of FPR1, FPR2, and FPR3 in BC cells by RT-qPCR." (PMID 36414640, 2022). "In particular, its pro-tumor mechanism of action can be due to the ability to bind the formyl peptide receptors (FPRs), in particular the isoforms FPR1 and FPR2." (PMID 36230687, 2022). "The expression levels of the distinct genes of the RvD pathway ALOX15, ALOX15, FPR2, GPR18, GPR32, HPGD and PTGR1 were leveraged from 516 bulk tumor HNSC RNA-seq data, profiled by TCGA and plotted as a heatmap of individual tumor samples." (PMID 35742918, 2022). "In these inflammatory cells, we verified a significant up-regulation of ANXA1 and FPR2/ALX expression in the peritumoral and tumor samples compared with the corresponding control tissues." (PMID 25490767, 2014). "Thus, FPR2 promotes EOC progression by simultaneously enhancing cancer cell mobility through RhoA activation and fostering a pro-tumor immune environment via M2 macrophage polarization." (PMID 40330466, 2025). "Additionally, it has been reported that gastric cancer tissues exhibit high expression of FPR2, activating the MAPK/ERK pathway, which promotes tumor progression and correlates with poor patient survival." (PMID 40733247, 2025). "Additionally, pro-tumor TANs were also recruited to the tumor area and interacted with Epi_10_CYSTM1, as well as Epi_07_CAPS and Epi_12_RRAD cells, via the ANNEXIN-to-FPR1/FPR2 signaling pathway." (PMID 40066698, 2025). "As the progression of metastasis requires collusion between cancer cells and localized accumulations of myeloid cells, the findings in this study advocate that ANXA1 in the tumor microenvironment is partially responsible for recruitment of infiltrating microglia through activation of FPR1 and FPR2." (PMID 35382852, 2022). "Importantly, when FPR2 or P2X7R were inhibited, a strong reduction in tumor size and circulating tumor cells was observed in several in vivo models of PDAC." (PMID 33530455, 2021). "To illustrate the role of FPR2 in vivo, we established tumour xenografts inoculated subcutaneously with SKOV3 cell lines (NC group) and SKOV3−shFPR2 cell lines (KD group) and then recorded and analysed the tumour volumes and tumour weights in each group." (PMID 34930387, 2021). "Indeed, pharmacological inhibition of formyl peptide receptor 2 (FPR2) and/or P2X purinoceptor 7 receptor (P2X7R) on CSCs which are the receptors of hCAP-18/LL-37 inhibited tumor formation in a PDAC mouse model." (PMID 32509781, 2020).
tumor (continued). "We observed strikingly increased expression of Fpr2 in XO mice, a marker for M1 macrophages and/or inflammation, whereas XDH ki mice expressed higher levels of arginase (arg), a marker for M2 macrophages within the tumor." (PMID 31659168, 2019). "Coordinately, polarized TAMs secrete the antimicrobial peptide hCAP-18/LL-37, which consequently binds to its receptors (formyl peptide receptor 2 (FPR2) and P2X purinoceptor 7 receptor (P2X7R)) to enhance CSC self-renewal, invasion, and tumor-initiating properties." (PMID 26980947, 2016). "FPR2-dependent STK10 phosphorylation could mediate cell proliferation and tumor progression." (PMID 32471307, 2020). "FPR-2 rather than FPR-1, has been involved in tumor progression and metastases of several tumors." (PMID 26312765, 2015).
infection (43 papers, 2008 to 2025). The state of being infected such as from the introduction of a foreign agent such as serum, vaccine, antigenic substance or organism. "Studies on Fpr2/3 knockout mice suggested increased susceptibility to infection, uncontrolled inflammation, and pulmonary dysfunction compared to wild-type animals." (PMID 39026356, 2024). "Mice deficient in Fpr2 had a lower inflammatory response supported by decreased soluble mediators and alleviated tissue injury at 12 h post-infection." (PMID 36776849, 2023). "In this study, we evaluated the roles of AnxA1 and Fpr2 in a mouse model of S. suis meningitis created via intracisternal infection in Fpr2-deficient (Fpr2−/−) and wild-type (WT) mice." (PMID 33318141, 2021). "In this study, we demonstrated that infection of WT mice with C. rodentium caused an increase in apical Fpr2 localization in colonic epithelial cells." (PMID 31234710, 2019). "In the present study we found upregulation of genes that encode the fMLP receptors (FPR1 and FPR2) in rabbit lungs as early as 3 hours after infection with HN878." (PMID 23958185, 2013). "FPR2 has been implicated in various human diseases, including infections, inflammation, and cancer." (PMID 37322488, 2023). "Fpr2 deficiency increased neutrophil recruitment in the brain at 6 and 14 h after infection." (PMID 33318141, 2021). "Among them, the main role of Fprs in pathogenic infection is Fpr1/Fpr2 mediated neutrophil recruitment in bacterial infection, that is, in L. monocytogenes infection, Fpr1/2 directly chemoattract neutrophils through the receptor itself before CXCL1/2 is produced." (PMID 34899755, 2021). "In addition to classic chemokines, the gene Fpr2, which encodes a receptor for the potent neutrophil chemoattractant formyl-methionyl-leucyl-phenylalanine (fMLPR), is also upregulated by infection in a phase-dependent manner (DFC of 5.7)." (PMID 30134832, 2018). "Interestingly, healthy FPR2-/- mice had elevated basal levels of IL-10, which could be related to a lower risk of mortality during the acute phase of infection." (PMID 34784372, 2021). "To assess the regulatory role of Fpr2 in inflammation induced by S. suis infection, we measured the levels of inflammatory mediators by quantitative real-time PCR and enzyme-linked immunosorbent assay (ELISA) and conducted histopathological studies at 14 h after infection in WT and Fpr2−/− mice." (PMID 33318141, 2021). "This could be an example of the intricate interplay between bacteria and host immunity in that lower levels of PSM peptides recruit neutrophils to the site of infection via FPR2 and that higher levels (e.g., close to the site of infection and/or high numbers of bacteria) instead cause NET formation." (PMID 28337204, 2017). "In S. aureus-induced infections, the activation of FPR1 and FPR2 increases the migration of neutrophils to infection sites and enhances bacterial phagocytosis." (PMID 41170422, 2025). "Transcriptional profiles of the genes CD38, Gpr18, Fpr2 (markers of classically activated macrophages), Arg1, and Egr2 (markers of alternatively activated macrophages) are significantly activated after infection with all viruses." (PMID 38473707, 2024). "Wildtype C57BL/6 mice were treated with the FPR2 antagonist WRW4 (1 μM) or PBS 30 minutes prior to infection with L. major alone or in combination with LeishEXO." (PMID 39076982, 2024). "Infection led to a significant reduction in claudin-5 fluorescence intensity in WT and FPR2-KO mice (**** p < 0.0001; two-way ANOVA followed by the Bonferroni test)." (PMID 39768195, 2024). "In vitro work corroborated these findings, indicating that FPR2 blockade inhibits LeishEXO-mediated enhancement of macrophage infections, exhibiting similar infection rates to cells incubated with L. major alone." (PMID 39076982, 2024).